RFTN2 (raftlin family member 2)
Description:
Upon bacterial lipopolysaccharide stimulation, mediates clathrin-dependent internalization of TLR4 in dendritic cells, resulting in activation of TICAM1-mediated signaling and subsequent IFNB1 production. May regulate B-cell antigen receptor-mediated signaling.
Synonyms: C2orf11; FLJ30574; Raftlin-2
Tractability: Antibody: UniProt places it where antibodies can reach, with medium confidence; its Gene Ontology location is reachable by antibodies, with medium confidence; the Human Protein Atlas places it where antibodies can reach.
Gene: Protein-coding gene on chromosome 2 (197,568,224 to 197,676,051, reverse strand). Ensembl gene ENSG00000162944.
Subcellular location: Cell membrane
Subcellular location (Human Protein Atlas): Plasma membrane
Gene Ontology:
Molecular function: protein binding
Cellular component: plasma membrane
Genetic constraint (gnomAD): Loss-of-function variants: 20 observed, 29.87 expected, observed/expected ratio (o/e) 0.67, 90% interval 0.47 to 0.97. The upper end of that interval is the gene's LOEUF score, 0.97, which puts it in group 4 of 6, group 1 being the genes least tolerant of losing a copy. Missense variants: 358 observed, 406.32 expected, observed/expected ratio (o/e) 0.88, 90% interval 0.81 to 0.96. Synonymous variants: 141 observed, 151.53 expected, observed/expected ratio (o/e) 0.93, 90% interval 0.81 to 1.07.
Homologues: Orthologues: chimpanzee RFTN2 (99% identical), macaque RFTN2 (97% identical), rabbit RFTN2 (87% identical), dog RFTN2 (86% identical), pig RFTN2 (86% identical), mouse Rftn2 (79% identical), rat Rftn2 (78% identical), guinea pig RFTN2 (60% identical), zebrafish rftn2 (42% identical). Paralogues in human: RFTN1 (30% identical).
Diseases named in the same sentence as RFTN2 in open-access papers:
RFTN2 is named in the same sentence as 10 diseases in open-access papers, as found by Europe PMC text mining. Sharing a sentence is not in itself a finding about the gene and the disease. The quoted sentences say what the papers report.
bipolar disorder (1 paper, 2024). A disorder of the brain that causes unusual shifts in mood, energy, activity levels and the ability to carry out day-to-day tasks. "Genes that were associated with brain volumes, depression, and schizophrenia or bipolar disorder includedAC011997.1,AKT3,BANK1,BOLL,DCC,HSPD1,HSPE1,HSPE1-MOB4,MOB4,PLCL1,RFTN2,SF3B1, andTRPS1." (PMID 40800518, 2024).
melanoma (1 paper, 2025). A malignant, usually aggressive tumor composed of atypical, neoplastic melanocytes. "Higher levels of RFTN2 and ITGB2 transcripts are also found in metastatic human melanomas compared with primary skin tumors." (PMID 39819494, 2025).
metastatic melanoma (1 paper, 2025). A melanoma that has spread from its primary site to another anatomic site. "In addition, BIN2, CMTM8, CXCL10, HCLS1, ITGB2, PTPN2, and RFTN2 were expressed at significantly higher levels in our B16 brain-derived variants compared with the parent B16-F0 and are also upregulated in human metastatic melanomas compared with primary cutaneous tumors." (PMID 39819494, 2025).
tumor (1 paper, 2012). "Other candidate genes, such as Des, Ccdc108, Slc40a1, or Rftn2, also found in the Lsktm1 locus, might act synergistically with Igfbp genes to confer the tumor phenotype." (PMID 22973541, 2012).
RFTN2 also shares sentences with these, for which no sentence is quoted: depression (1 paper); hepatocellular carcinoma (1); prostate carcinoma (1); sarcopenia (1); schizophrenia (1); skin tumors (1).